CD4 (CD4 molecule)
Diseases named in the same sentence as CD4 in open-access papers (continued):
Sharing a sentence is not in itself a finding about the gene and the disease.
cancer (continued). "We found that MTA2 was positively associated with Type 2 helper T cells (a subset of CD4+ T cells) in most cancers." (PMID 37371463, 2023). "Then, the associated carcinomas were characterized not only by a decreased infiltration of CD4+ T cells but also by an increased infiltration of CD8+ T cells." (PMID 37086293, 2023). "N-myc downstream-regulated gene 1 (NDRG1), an anti-cancer therapeutic target, has previously been implicated as a CD4+ T cell clonal anergy factor." (PMID 36357486, 2022). "Cancer-associated fibroblasts, endothelial cells, hematopoietic cells, resting memory CD4+ T cells in patients at high risk of GC were significantly abundant versus low-risk cases." (PMID 35382776, 2022). "Cancer associated fibroblasts (CAFs) of ATLL play an important role for CD4 T-cell proliferation via FGF7-FGF1 and PDGFA-PDGFRA/B signaling, and CAFs, particularly EGR-enriched, are also associated with CD8 and NKT expansion by EGFR." (PMID 35464471, 2022). "It is associated with a higher risk of cancer when CD4 counts are low in HF in the broader HIV population, according to recent studies." (PMID 36237744, 2022). "In contrast, NEIL3 expression was significantly associated with active CD4 T cells and Th2 cells, which implies cancer recurrence in most tumors." (PMID 36612106, 2022). "Relevant studies have shown that the number of CD4+ T lymphocytes in patients continues to decrease, and the decline in cellular immune function is the main cause of opportunistic infections and malignant tumors in the body." (PMID 35694588, 2022). "Accordingly, the presence of intratumoral IL-17A+ IL-23R+ IL-6+ CD4+ T cells was described to be associated with the development of colitis-associated cancer." (PMID 36428508, 2022). "We adopted multiple immune deconvolution methods to find a statistically positive correlation of HOXB4 expression with B cells, macrophages, CD8+ T cells, CD4+ T cells, dendritic cells, neutrophils, and cancer-associated fibroblasts." (PMID 35211403, 2022). "The positive association of risk score with NK T cells, cancer-associated fibroblasts, Tregs, M1 macrophages, CD4 + T cells, Th1 cells etc. was shown in the resutls." (PMID 36439501, 2022). "The results showed that 80.4% cells in cancer associated with T3/T4, in which naïve CD4 + T cell accounts for 21.5%, macrophage accounts for 11.5% and Treg accounts for 5%." (PMID 36221095, 2022). "Together, these findings provide evidence that TSLP induction to drive CD4+ T cell activation can potentially be an effective therapeutic strategy to prevent cancer development and progression in high-risk patients." (PMID 36467403, 2022). "High activity of priming and activation, recruitment of CD4 T cells, dendritic cells, T cells, and Th1 cells; infiltration of immune cells into tumors; and recognition of cancer cells by T cells were found in high-risk subset compared to the low-risk subset." (PMID 36860211, 2022). "Immune infiltration analysis indicated that the risk score was significantly inversely correlated with infiltration of CD8+ T cells and CD4+ T cells and positively correlated with macrophages and cancer-associated fibroblasts." (PMID 36425941, 2022). "Positive associations between ITGAV expression and resting CD4 memory T cells, M1 macrophages, and M2 macrophages were observed in more than ten cancers." (PMID 35927660, 2022). "The immune cells enrichment analysis by multiple algorithms demonstrated that high risk group was positively correlated with the enrichments of CD8+ T cell, CD4+ T cell, B cell, NK cell, macrophage and cancer associated fibroblast." (PMID 36467996, 2022). "We found that the infiltration levels of CD8+T cells, CD4+Th2 cells, CD4+Treg cells, and cancer-associated fibroblasts increased with elevated RIOK2 expression." (PMID 36518977, 2022). "In various cancers, resting CD4 memory T cells were associated with increased overall survival, so the frequency of resting CD4 memory T cells predicted better survival." (PMID 36333388, 2022).
cancer (continued). "PLWH who initiate ART at CD4 counts less than 350 cells/mm3 or with an AIDS defining condition are known to be at increased risk of developing cancer." (PMID 34873875, 2022). "First, we compared the correlation of risk score with different immune cells based on 7 algorithms, and the results showed that macrophages, cancer-associated fibroblasts, and CD4+ T cells were significantly positively correlated with risk score." (PMID 36248799, 2022). "The expression of FDX1 was positively correlated with the infiltration level of CD8+T cells, NK cells and neutrophil cells but negatively correlated with CD4+T cells and cancer associated fibroblasts." (PMID 36523779, 2022). "The risk of being diagnosed with cancer increased with older age and lower CD4 cell count at ART initiation." (PMID 34873875, 2022). "Dysfunctional EZH2 is associated with the development of multiple cancer types in humans and can promote immune evasion by inhibiting intra-tumoral antigen presentation, immune cell migration, and enhancing CD4+ T regulatory cell (Treg) suppressive activity." (PMID 36532284, 2022). "Recent studies have demonstrated that a higher density of CD4 naive T cells, regulatory T cells, and M2 macrophages is closely associated with a worse clinical prognosis in many malignant tumors, including COAD." (PMID 36699444, 2022). "AATF expression levels in various cancer types were significantly correlated with the infiltration levels of cancer-associated fibroblasts, endothelial cells, CD4+ T cells, B cells, myeloid dendritic cells, eosinophils, and macrophages." (PMID 36275893, 2022). "Immune infiltration analysis indicated that the signature was significantly inversely correlated with infiltration of CD8+ T cells and CD4+ T cells while positively correlated with macrophages and cancer associated fibroblasts." (PMID 36425941, 2022). "Clinical outcomes in various cancers are correlated with changes in the compositions of CD8 and CD4 positive T cells, macrophages, and cancer-associated fibroblast infiltration in the TME." (PMID 36591468, 2022). "CD4+ T cells play a role in activating adaptive immune responses against cancer, while the conversion to immunosuppression is mainly caused by CD4+ regulatory T cell (Treg) cells." (PMID 35158758, 2022). "While in READ, HSF1 expression was negatively correlated with CD4 + T cell and positively correlated with cancer associated fibroblast (CAF), CD8 + T cell and NK cell." (PMID 35006040, 2022). "The TME cluster-B was characterized by an increase in the infiltration of cancer-associated immune cells, such as Th1 cells, CD4 T cells, CD8 T cells, B cells, macrophages, and plasma cells." (PMID 36360212, 2022). "LA caused more oxidative damage than other free FAs (such as Palmitic acid), which mediated the selective loss (death) of CD4+ T lymphocytes in the liver, accelerating the occurrence of cancer." (PMID 35720307, 2022). "The levels of cancer‐associated fibroblasts (CAFs) and macrophages were elevated in PCa patients aged ≥60 years, whereas the levels of CD4+T cells and CD8+T cells were decreased in PCa patients aged ≥60 years (all p < 0.05)." (PMID 35535438, 2022). "HIV predominantly affects and depletes CD4 T cells, leading to a gradual loss of immune fitness and susceptibility to opportunistic pathogens and cancers." (PMID 36358898, 2022). "CD8+ T cells can be targeted to kill cancer cells, while CD4+ T cells can maintain and enhance the underlying immune function." (PMID 35494032, 2022). "Aberrant CD4 T cell responses are associated with multiple immunopathologies, but they are also critical components of protective immune responses against cancers and pathogens." (PMID 36358898, 2022). "Regulatory T cells (Treg) associated with cancer progression that come from the transformation of traditional CD4+ T cells have the ability to suppress immune responses and accumulate in both animal models and cancer patients." (PMID 35140720, 2022).
cancer (continued). "In HR+ BC, FOXP3+ CD4+ TILs were associated with higher grade cancers, lymph nodes involvement, and worse prognoses; however, it must be noted that this prognostic significance was lost in multivariate analysis." (PMID 36230808, 2022). "Further analysis suggested that the expression of NUTF2 expression was correlated with the infiltration of immune cells, such as CD8+ T cells, effector memory CD4+ T cells, and cancer-associated fibroblasts in kidney renal clear cell carcinoma." (PMID 35155261, 2022). "Generally, cytotoxic CD8+ T cells and CD4+ helper T cells exhibit antitumor effects and are associated with favorable prognoses in various types of cancers." (PMID 35454945, 2022). "Most of the cancer types showed significant positive associations between angiogenesis scores and infiltration levels of macrophages, NK cells, as well as CD4+ T cells, implying that angiogenesis scores are associated with a hot TME." (PMID 35155426, 2022). "Levels of PSEN1 were negatively correlated with infiltrating CD8+ T (p<0.05) and CD4+ T helper (Th) 1 cells (p<0.001), while positively correlated with regulatory T cells (Tregs) (p<0.001) and cancer associated fibroblasts (CAFs) (p<0.001)." (PMID 36059511, 2022). "In our analysis, we discovered that 14 malignancies were strongly associated with CD4+ T cells, 11 cancers were significantly associated with B cells, and 11 cancers were significantly associated with resting mast cells." (PMID 35359421, 2022). "TCR transgenic CD4+ T cells targeting HLA-DPB1*04:01 restricted melanoma-associated antigen A3 (MAGE-A3) also showed efficiency in various cancer types." (PMID 35269735, 2022). "The abnormal activity of a few notable STPs (Notch and TGFβ) suggests that CD4+ T-cells have changed into regulatory T-cells, which inhibit the immune response against cancer and have been associated with resistance to immunotherapy." (PMID 35158758, 2022). "Second, we explore the EPIC, MCPCOUNTER, XCELL, TIDE, CIBEREORT, and CIBEREORT-ABS algorithms to investigate T-cell CD4+, cancer-associated fibroblasts, T-cell CD8+, T-cell regulators, and macrophages." (PMID 36338742, 2022). "This immunosuppressive subset of CD4+ cells has recently been associated with resistance to treatment with novel cancer immunotherapies such as anti-CTLA-4 and anti-PD-1." (PMID 35714487, 2022). "The association of severe CD4+ suppression with cancer is consistent with the attribution of the benefits of cART in the prevention of opportunistic cancers in the restoration of the adaptive immune response." (PMID 36551614, 2022). "HLA class II molecules like HLA-DPB1, HLA-DRA, HLA-DRB1, and HLA-DQB1 are associated with antigen processing and presentation to CD4+ T cells, and the down-regulation of these genes is related to poor prognosis of cancers." (PMID 36417424, 2022). "The role of CD4+ T cells is increasingly being studied that stromal infiltration of CD4+ T cells in cancers is associated with better OS and disease-specific survival." (PMID 35480320, 2022). "Along these lines, findings of the present investigation on the prognostic impact of vessels associated TILs strongly support the reported relevance of CD4+ lymphocytes in the immune-vascular crosstalk critically implicated in cancer growth and regression." (PMID 35805021, 2022). "CD8+ and CD4+ T cells, cancer-associated fibroblasts, cancer cells, and dendritic cells are able to secrete CXCL13, and CD8+ and CD4+ T cells, B cells, and cancer cells express CXCR5." (PMID 35053457, 2022). "Of these, cancer-associated fibroblasts (CAFs) had a higher proportion, while CD4 T cells had a lower infiltration in the HS group." (PMID 36439479, 2022).
cancer (continued). "A similar pattern was observed for CD4 wherein high-risk dysplastic and carcinoma samples showed higher infiltration compared to normal tissues (p < 0.01)." (PMID 36009387, 2022). "In CD4+ cells HIV-1 was reported to preferably integrate into cancer-associated genes or cell cycle regulation genes dysregulation of which can lead to cancer formation as was described for other retroviruses." (PMID 33467638, 2021). "CD4+T lymphocytes destruction leads to severe immune deficiency, which causes various opportunistic infections and malignant tumors." (PMID 34917579, 2021). "11,805 cell transcriptomes were profiled, cell landscapes of PTC were composed of malignant follicular epithelial cells (MFECs), CD8+ and CD4+ T cells, B cells, vascular endothelial cells, fibroblasts and cancer-associated fibroblasts (CAFs)." (PMID 34790166, 2021). "For subsequent subtyping, we focused on CD8+ effector/cytotoxic and CD4+ helper T-cells, as their presence is associated with favorable outcomes in several cancers." (PMID 34572789, 2021). "T cells are instrumental in fighting cancer, and a low CD4/CD8 T cell ratio is associated with aging, which is accelerated upon various stressors." (PMID 35008253, 2021). "Comparative EPIC data from the metastatic CM showed that cancer-associated fibroblasts, CD4+ T cells, CD8+ T cells, endothelial cells, and natural killer (NK) cells had higher immune infiltration levels in the LAGE3low group than in the LAGE3high group." (PMID 33829062, 2021). "Cells with antitumor effects, such as CD8+ T cells, CD4+ T cells, B cells and plasma cells, were higher in the low-risk group, while cells with pro-cancer functions, such as M2 macrophages and cancer-associated fibroblasts, were higher in the high-risk group." (PMID 34587919, 2021). "VIRMA was significantly associated with Cancer associated fibroblast (r = 0.285, p = 1.05e–04), Myeloid dendritic cell (r = 0.209, p = 4.92e–03), CD4+ T cell (r = 0.233, p = 1.61e–03), Neutrophil (r = 0.192, p = 9.91e–03)." (PMID 33748145, 2021). "In the GSEA, we identified that the specific gene sets associated with the downregulation of CD8+ T cells, CD4+ T cells and B cells, which play an important role in the complete elimination of cancer cells, were linked to high MMP-11 expression." (PMID 34038440, 2021). "In BLCA, MALAT1 RNA level correlated with CD8 + T cell, CD4 + T cell, DC cell, Tregs cell, Mast cell, cancer-associated fibroblast, common lymphoid progenitor, eosinophil, MDSC, T cell NK, and T cell follicular helper cell infiltration." (PMID 34308750, 2021). "Human immunodeficiency virus (HIV) infects the body’s dendritic cells (DCs) and macrophages and activates CD4+ T cells, causing destructions of the immunal system, and leading to a significant increment of incidence of certain cancers." (PMID 33882973, 2021). "More interestingly, mast cell activation, and resting memory CD4 T cells are reported to be inextricably linked to cancer development." (PMID 34222004, 2021). "Th1 and Th2 CD4+ T cells were most positively associated with the HSF1 expression in these different cancers." (PMID 34239690, 2021). "We confirmed that CD44+ was acquired in the livers of mice with HCC, that it was predominantly expressed in macrophages, and that its expression was closely associated with expansion of CD4 T cells which characterise a cancer permissive environment." (PMID 34408183, 2021). "CD4+ was associated with a lower risk of death for cancer of the oropharynx (pooled HR = 0.52; 95% CI: 0.31–0.89), but not of the oral cavity (pooled HR = 0.98; 95% CI: 0.96–1.00) and hypopharynx (pooled HR = 0.77; 95% CI: 0.49–1.20)." (PMID 33668519, 2021). "MYBL2 was known to overexpress and associate with poor patient outcomes in many cancer entities; its expression positively correlated with CD4+ T cell infiltration but negatively correlated with B cell infiltration." (PMID 34489925, 2021).
cancer (continued). "Naturally occurring HLA-II-restricted CD4 T cell responses against TERT peptides were detected in patients with various types of cancer and were associated with a good prognosis." (PMID 34144673, 2021). "In the START trial, which randomized PLHIV with CD4 > 500/mm3 to immediate cART initiation or cART deferral until CD4 dropped < 350/mm3, immediate cART initiation reduced the risk of all cancer by 64%." (PMID 34830846, 2021). "HIV-1 infection promotes systemic diminution of CD4+T cells, which, in turn, results in impaired cell-mediated immunity, a wide spectrum of cancers, and increases susceptibility to opportunistic infections." (PMID 33451365, 2021). "Increasing evidence points towards CD4+CD25+Foxp3+ Tregs having a pathogenic role in cancer development and metastasis, primarily through inhibiting host cancer-associated-antigen adaptive immunity." (PMID 34831195, 2021). "Activated CD8+ T cells, γδ-T cells, and CD4+ Th1 cells are important in regulating type I immune responses, while Th2, Tregs, and Th17 are frequently associated with cancer progression and a worse prognosis." (PMID 34063848, 2021). "We found by TIMER analysis that WDR4 levels are significantly associated with the infiltration of CD8+ and CD4+ T cells in in 21 types of cancer, B cells in 14 types, dendritic cells in 19 types, neutrophils in 15 types, and macrophages in 14 types." (PMID 34282052, 2021). "FABP5 has also been associated with the development of diverse types of cancer, indicating the importance of considering metabolic aspects of CD4 + T cells in the TME." (PMID 34026764, 2021). "In LUAD and BLCA, MALAT1 were both associated with CD8 + T cell, CD4 + T cell, DC cell, Tregs cell, Mast cell, cancer-associated fibroblast, common lymphoid progenitor, eosinophil, MDSC, and T-cell follicular helper cell infiltration." (PMID 34308750, 2021). "The relative risk of cancer associated with severe CD4 suppression was 6.19 (p = 0.0002), 2.33 (p = 0.0042), and 1.77 (p = 0.0305) at 1, 5, and 10 years of ART, respectively." (PMID 33803641, 2021). "The results of the EPIC algorithm showed that cancer associated fibroblast, T cell CD4+, T cell CD8+, macrophage, and uncharacterized cells were significantly different." (PMID 34267780, 2021). "This study identified delayed commencement of ART and severe CD4 lymphocyte nadir at any point during the life of CLWH as critical risk factors for developing cancer." (PMID 33803641, 2021). "It is worth noting that WTAP is associated with cancer-related fibroblasts, myeloid dendritic cells, CD4+ T cells, neutrophil regulatory T cells, CD8+ T cells and macrophages." (PMID 33748145, 2021). "Any significant relation between the immunovirological status (expressed by CD4+ T-cell count and viral load) and cancer risk was found." (PMID 34336735, 2021). "The risk of cancer associated with delayed ART was also present after adjusting for CD4 nadir, (aOR = 2.51, 95% CI 1.38, 4.58, p = 0.0027)." (PMID 33803641, 2021). "We found that CD4+ T cells showed a lower proportion in tumors than in normal tissues, while cancer-associated fibroblasts showed a higher proportion in tumors than in normal tissues." (PMID 34489925, 2021). "This study also provides preliminary evidence for starting ART as early as possible and preventing severe CD4 lymphocyte suppression to reduce the risk of cancer in CLWH." (PMID 33803641, 2021). "The association of severe CD4 suppression with cancer in the early years of HIV treatment of these children is consistent with the attribution of the benefits of ART in the prevention of opportunistic cancers to the restoration of the adaptive immune response." (PMID 33803641, 2021). "We found that the IL-6- and IL-1B-encoding genes were dramatically overexpressed in CD4+ T cells due to exhaustion induced by cancer cells." (PMID 34439305, 2021).